ADAM12 (ADAM metallopeptidase domain 12)
Diseases named in the same sentence as ADAM12 in open-access papers (continued):
Sharing a sentence is not in itself a finding about the gene and the disease.
colorectal tumor (1 paper, 2021). "In colorectal tumors, ADAM12 may play vital roles in regulating the ECM and the recruitment of immune cells, and we postulate that it may become a reliable biomarker for the immunotherapy response and prognosis of patients with COAD." (PMID 34604068, 2021). "In colorectal tumors, ADAM12 may play vital roles in regulating the ECM and the recruitment of immune cells, and we suggest that ADAM12 will become a reliable biomarker for determining response to immunotherapy and the prognosis of patients with COAD." (PMID 34604068, 2021). "Overall, our results clearly indicated that ADAM12 is closely related to the immune cell penetration of CRC and may be a new target worthy of further investigation in the field of colorectal tumor immunotherapy." (PMID 34604068, 2021).
COVID-19 (1 paper, 2022). A disease caused by infection with severe acute respiratory syndrome coronavirus 2. "We found that the expression of the antiviral genes negatively correlated (except ADAM7, ADAM11, ADAM12, ADAM18, ADAM20, and ADAM29) with the HRCT score of the COVID-19 patients suggesting association of increased antiviral response with decreased disease severity." (PMID 36532041, 2022).
Dupuytren's disease (1 paper, 2014). "ADAM12 expression has been demonstrated in a number of malignant diseases 23, and also Dupuytren's disease." (PMID 24402778, 2014).
fragile X syndrome (1 paper, 2022). A genetic syndrome caused by mutations in the FMR1 gene which is responsible for the expression of the fragile X mental retardation 1 protein. "This set of genes included cancer oncogenes (CMYC, CKIT, BCL2, KRAS) and genes associated with different cancer types (ADAM12, ALOX5, SRSF6, VEGF12) as well as FMR1, associated with fragile X syndrome (OMIM: 300624), and SNX12, which is associated with neurodegenerative diseases." (PMID 35573091, 2022).
growth disorders (1 paper, 2023). "In addition, we found three new missense variants in PAPPA2, ADAM12 and EZH2, three genes related to growth disorders in different species including humans." (PMID 38017417, 2023).
head and neck cancer (1 paper, 2025). A primary or metastatic malignant neoplasm affecting the head and neck. "A study in head and neck cancer cells demonstrated that ADAM12 increased HER2 expression, HER2 inhibition decreased ADAM12 expression, and HER2 transfection increased ADAM12 expression suggesting there is a positive feedback loop between those two65." (PMID 39755747, 2025).
hydatidiform mole (1 paper, 2014). A gestational trophoblastic disorder characterized by marked enlargement of the chorionic villi, hyperplasia of the villous trophoblastic cells and hydropic changes. "The findings of the current study demonstrate that at 5−9+6 weeks gestation, in the complete spontaneous abortion, ectopic pregnancy and hydatidiform mole groups, ADAM12 levels are lower than that in the control group." (PMID 24830297, 2014). "Using the maternal serum ADAM12 level 5.45 ug/l as a cut-off value to predict hydatidiform mole, the sensitivity was 100.0% and the false-positive rate was 8.3%; the area under the curve (AUC) was 0.90." (PMID 24830297, 2014). "In the EP and the hydatidiform mole groups, ADAM12 levels were lower than the control group." (PMID 24830297, 2014).
Infertility (1 paper, 2022). "It has been suggested that MAP4K4 affects SH3PXD2A-binding enzymes ADAM12, ADAM15, and ADAM19, which has been shown to be associated with infertility in mutant mouse models." (PMID 36497065, 2022).
interstitial lung disease (1 paper, 2019). A diverse group of lung diseases that affect the lung parenchyma. "Interestingly, the serum ADAM12 levels may be associated with the initiation and progression of fibrosis, as well as the development of interstitial lung disease in SSc patients." (PMID 31582779, 2019).
intracranial aneurysms (1 paper, 2023). "In that regard, it is remarkable that ADAM12 was recently proposed as a diagnostic classifier for rupture of intracranial aneurysms." (PMID 37079380, 2023).
keratoconus (1 paper, 2020). A degenerative, structural disorder of the eye, characterized by a cone-shaped protrusion of the cornea. "Specifically, we selected seven keratoconus-susceptibility genes (CDH13, SMAD3, ADAM12, CSMD1, NRXN1, CPLX2, and WWOX) for further analysis." (PMID 32737415, 2020).
kidney cancer (1 paper, 2025). Primary or metastatic malignant neoplasm involving the kidney. "In conclusion, our results demonstrate that ADAM12 and CYP1B1 are highly expressed in CAAs of kidney cancer and that their expression linearly follows the body weight." (PMID 39806854, 2025). "We observed that ADAM12 and CYP1B1 downregulation has a deep impact on the proliferative ability and the invasiveness of RCC cells, pointing to a critical role of these genes in regulating tumor–stroma interplay and fostering kidney cancer in obese patients." (PMID 39806854, 2025).
laryngeal carcinoma (1 paper, 2019). Carcinoma that arises from the laryngeal epithelium. "As a result of the high expression of ADAM12 and the low expression of CHES1 in laryngeal carcinoma, they analyzed the presumed diagnostic values of the ratios of expressions of CHES1 and ADAM12 genes by setting the threshold of the ratio of the two genes (ADAM12/CHES1) at 0.4." (PMID 31214487, 2019). "Therefore, it is expected that the ratio of ADAM12/CHES1 can be taken as a molecular marker to distinguish between tumor and non-tumors, and that it may become the best diagnostic indicator for laryngeal cancer." (PMID 31214487, 2019).
Lewis lung carcinoma (1 paper, 2021). "To investigate the effect on the inhibition of ADAM12 in tumor growth, we performed MTT assay to check the anti-proliferative activity of KB-R7785 against 3LL, a highly metastatic Lewis lung carcinoma cell." (PMID 33804570, 2021).
limb ischemia (1 paper, 2022). A ischemia that involves the limb. "In an experimental model of limb ischemia in diabetic mice, inhibiting miRNA-29a upregulated the expression of the ADAM12 gene, coding for the disintegrin and metalloproteinase domain-containing protein 12, which improved perfusion recovery." (PMID 36233355, 2022).
liver cirrhosis (1 paper, 2020). "Increased expression of ADAM12 was detected in activated HSCs and in liver tissue sections from patients suffering from liver cirrhosis or HCC, suggesting that ADAM12 has a tumour-promoting role in the liver by actively remodelling the extracellular matrix." (PMID 32698506, 2020).
lobular carcinomas (1 paper, 2007). "Several genes encoding proteins involved in actin, calcium and metal ion binding were downregulated (MYBPC1, DST, PIP, CA2), and some genes with the same function (BGN, ADAM12) were upregulated in lobular carcinomas." (PMID 17389037, 2007).
lung squamous cell carcinomas (1 paper, 2006). "We describe for the first time an increased production of ADAM-12 both at the mRNA and protein levels in human lung squamous cell carcinomas and adenocarcinomas." (PMID 16495931, 2006).
lymph node metastasis (1 paper, 2021). "ADAM12 overexpression was significantly associated with the cancer stage, depth of invasion, lymph node metastasis, distant metastasis, and poor survival in CRC patients." (PMID 33923541, 2021). "We observed that ADAM12 expression was significantly associated with cancer stage, depth of invasion, lymph node metastasis, and distant metastasis (p < 0.001, p = 0.026, p = 0.003, and p < 0.001, respectively)." (PMID 33923541, 2021). "Overexpression of ADAM12 was significantly associated with the cancer stage, depth of invasion, lymph node metastasis, distant metastasis, and poor survival in patients with CRC." (PMID 33923541, 2021).
malignant glioma (1 paper, 2021). A grade III or grade IV glioma arising from the central nervous system. "Upregulation of LINC01614, induced by SP1, promotes malignant glioma progression by modulating the miR-383/ADAM12 axis." (PMID 35047016, 2021).
muscular dystrophy (1 paper, 2025). Muscular dystrophy (MD) refers to a group of more than 30 genetic diseases characterized by progressive weakness and degeneration of the skeletal muscles that control movement. "ADAM12, a disintegrin and metalloproteinase typically associated with skeletal muscle development and regeneration, has been found to mitigate muscle degeneration and inflammatory responses in patients with muscular dystrophy." (PMID 40440631, 2025).
myocardial infarction (1 paper, 2019). Gross necrosis of the myocardium, as a result of interruption of the blood supply to the area, as in coronary thrombosis. "A recent study of single cell analyses revealed the up-regulation of fibrotic gene profiles: Postn, Acta2, Adam12, Lox, Wisp1, and Ddr2 during cardiac remodeling in response to angiotensin II and after myocardial infarction." (PMID 31417912, 2019).
neuroendocrine pancreatic tumor (1 paper, 2023). "To determine whether ADAM12+ MSCs develop in spontaneously occurring tumors, we crossed ADAM12-GFP mice with Rip-Tag2 mice, a mouse model of neuroendocrine pancreatic tumor, or with TRAMP mice, a mouse model of prostate adenocarcinoma." (PMID 37798557, 2023).
oral cancer (1 paper, 2023). "However, this may be cell or cancer-type dependent, as a few previous studies suggested that ADAM12 expression correlated with radiosensitivity in tongue, larynx, and oral cancer cells." (PMID 37495855, 2023).
osteophytes (1 paper, 2013). "The relation of ADAM12 genetic variants to osteophytosis observed in the current study is supported by our previous research, demonstrating association between ADAM12 and osteophytes on gene and protein level." (PMID 23606964, 2013).
osteoporosis (1 paper, 2023). A condition of reduced bone mass, with decreased cortical thickness and a decrease in the number and size of the trabeculae of cancellous bone (but normal chemical composition), resulting in increased fracture incidence. "Second, our negative results could not totally deny the potential of ADAM12, ADAM19, ADAM23 and ADAMTS6 as biomarkers for osteoporosis due to the weakness of MR analysis in identifying non-linear relationship." (PMID 37468870, 2023).
pancreatitis (1 paper, 2012). Inflammation of the pancreas. "Consistent with our exon array result, ADAM12 mRNA was highly overexpressed in the pancreatic control fibroblast derived from a pancreatitis specimen (SC3) and nine CAFs relative to the control fibroblasts HPNE and SC2." (PMID 22984426, 2012).
pituitary tumor (1 paper, 2021). A benign or malignant neoplasm affecting the pituitary gland. "ADAM12 overexpression is associated with pituitary tumor invasiveness, while its silencing prevents such biological behavior." (PMID 33790868, 2021). "Furthermore, different other non-classical molecules related to EMT have been characterized as part of the mechanisms allowing invasiveness in pituitary tumors, such as ADAM12 (a disintegrin and metalloprotease 12), which has been postulated as an EMT inducer in these tumors." (PMID 33790868, 2021).
prostate adenocarcinoma (1 paper, 2023). "In this setting, we observed YFP+αSMA– or YFP+αSMAmid cells at the tumor margins of large prostate adenocarcinomas in 30-week-old TRAMP mice, demonstrating that ADAM12+ cells induced in early tumors generate a peritumoral lineage that is maintained during tumor progression." (PMID 37798557, 2023).
pterygium (1 paper, 2022). A wedge-shaped fibrovascular lesion arising from the bulbar conjunctiva and extending to the cornea. "We found that hsa_circ_0002406 might upregulate FN1 and ADAM12 by sponging miR-26b-5p and miR-1-3p, respectively, thus promoting EMT in pterygium." (PMID 36398070, 2022).
pulmonary fibrosis (1 paper, 2014). Chronic progressive interstitial lung disorder characterized by the replacement of the lung tissue by connective tissue, leading to progressive dyspnea, respiratory failure, or right heart failure. "Studies suggest an important role of both ADAM12 and WISP1 in pulmonary fibrosis." (PMID 24402778, 2014).
rhabdomyosarcoma (1 paper, 2006). A rare aggressive malignant mesenchymal neoplasm arising from skeletal muscle. "As an alternative splicing has been reported for ADAM-12 and as the secreted short form of ADAM-12 (ADAM-12S) was described to be expressed by tumours such as rhabdomyosarcoma and HU-1 cells, we assessed our tumour samples for the expression of ADAM-12L and ADAM-12S by specific RT–PCR." (PMID 16495931, 2006).
serous ovarian carcinoma (1 paper, 2022). "Of notable interest was the down-regulation of transcripts coding for metalloproteinases including ADAM12, a factor associated with an aggressive phenotype in high-grade serous ovarian carcinoma." (PMID 35562985, 2022).
squamous cell carcinoma (1 paper, 2024). A carcinoma arising from squamous epithelial cells. "Additionally, compared to control cells, human squamous cell carcinoma and cell lines from the same malignancies were shown to have higher levels of ADAM12 RNA." (PMID 39596804, 2024).
synovitis (1 paper, 2023). Inflammation of a synovial membrane. "Studies have shown that both mRNA and protein levels of ADAM12 are increased in the synovial tissues of OA-associated synovitis." (PMID 36855121, 2023).
tendinopathy (1 paper, 2013). "MMP2, MMP3, MMP8, ADAMTS2, ADAMTS4, ADAM12 and collagen type I expression were regulated in a similar manner in tendinopathy compared to the current study." (PMID 23830915, 2013). "ADAM12 was chosen as we had previously shown its regulation in tendinopathy." (PMID 23830915, 2013).
type 1 diabetes (1 paper, 2021). "ADAM12 is upregulated in ischemic mouse GA and contributes to post-ischemic perfusion recovery but its upregulation is impaired in ischemic GA of mice with type 1 diabetes and associated with poor post-ischemic perfusion recovery." (PMID 35008854, 2021). "Furthermore, we showed that impaired ADAM12 upregulation in ischemic GA of mice with type 1 diabetes was due to impaired downregulation of miR-29a, a miRNA that regulates ADAM12 expression in ischemia." (PMID 35008854, 2021).
ulcerative colitis (1 paper, 2025). An inflammatory bowel disease involving the mucosal surface of the large intestine and rectum. "PER2 downregulated a disintegrin and metalloproteinase 12 (ADAM12) expression by reducing its binding activity, thereby suppressing IFN‐γ production in CD4 + T cells of ulcerative colitis." (PMID 40911428, 2025).
tumor (119 papers, 2005 to 2026). "The radiogenomic features associated with disintegrin and metalloproteinase domain-containing protein 12 (ADAM12) expression in ccRCC include primary tumor size, ill-defined margins, tumor necrosis, and collecting system invasion." (PMID 40558291, 2025). "Several studies suggest that ADAM12 plays a key role in the remodeling of the extracellular matrix, which is an important hallmark of neoplastic disease (Park, 2021 #33; Zhu, 2022 #34)." (PMID 36675796, 2023). "Most prominently, ADAM12 is a biomarker for cancer-associated fibroblasts (CAF) found in the tumour stromal microenvironment." (PMID 35205743, 2022). "As a member of the ADAM family, ADAM12, like other members, is expressed at high levels in tumor tissues, and lower expression is associated with a better survival prognosis." (PMID 34604068, 2021). "A disintegrin and metalloprotease 12 (ADAM12) has been implicated in cell growth, tumor formation, and metastasis." (PMID 33923541, 2021). "A disintegrin and metalloprotease 12 (ADAM12) has been associated with tumor development and progression." (PMID 33923541, 2021). "In the current study, ADAM-12 was expressed in the nucleus of tumour parenchyma cells, which is probably associated with the high capacity of ACC for invasion and metastasis." (PMID 32386517, 2020). "ADAM12 was significantly higher expressed in tumor tissue, and high expression of ADAM12 was associated with worse survival following resection 25,26." (PMID 30442938, 2018). "A reduction in ADAM12 levels is likely to be caused by a diminished stromal activation, or a reduced tumor load." (PMID 30442938, 2018). "A previous report indicated that the expression of ADAM12 was associated with tumor aggressiveness and progression in HCC." (PMID 27270327, 2016). "Indeed, ADAM12 is a Zn2+ dependent, pleiotropic protein, also involved in tumor formation and progression, besides being implicated in the pathogenesis of liver fibrosis, hypertension, and asthma." (PMID 39806854, 2025). "Moreover, GSE53757 and GSE73731 data sets showed a significantly higher expression of ADAM12 in ccRCC tissues tightly associated with tumor stage and grade (p < 0.05)." (PMID 36717944, 2023). "EGFR signaling, which involves the mTOR pathway, is expressed in these tumors, and it is associated with tumor proliferation, invasive behavior, lower total resection, and epithelial-to-mesenchymal transition; this latter is also mediated by the ADAM12 metalloprotease." (PMID 37958702, 2023). "We investigated whether there was an association between primary tumor location and serum ADAM12 groups." (PMID 35413826, 2022). "The literature on the association between ADAM-12 and some malignant tumours, such as breast and prostate cancer, is vast, indicating its direct relationship with the pathophysiology of these neoplasms." (PMID 32386517, 2020). "Furthermore, its activation can regulate certain genes linked to tumor growth and aggressiveness, such as the disintegrin and metalloproteinase domain-containing protein 12 (ADAM-12)." (PMID 31319505, 2019). "Similarly, ADAM12 mRNA expression levels in the TCGA database (retrieved as merged values for different splice variants) were significantly higher in claudin-low tumors than in other tumor subtypes." (PMID 28148288, 2017). "Immunohistochemistry determined the localization of proteins such as COL4A2 in the stroma and ADAM12 in tumour cells." (PMID 40998421, 2025). "Co-culture assays showed that endothelial cells exposed to ADAM12-expressing tumour cells exhibited increased recruitment and capillary tube formation." (PMID 40427200, 2025). "Regarding our findings, several hub genes, including ADAM12, MET, THBS2, ZEB1, and ZEB2, have been previously implicated in PDAC progression, tumor invasiveness, and epithelial–mesenchymal transition (EMT)." (PMID 40728965, 2025).